INS (insulin)
Diseases named in the same sentence as INS in open-access papers (continued):
Sharing a sentence is not in itself a finding about the gene and the disease.
type 2 diabetes (continued). "To test if hyperfunctionality of β cells in βLKB mice declines with age, as seen in human type 2 diabetes and in some mouse models exhibiting enhanced insulin secretion, we measured glucose tolerance and serum insulin levels in βLKB mice up to 16 months after deletion." (PMID 26139601, 2015). "Therefore, understanding the molecular mechanism that regulates insulin sensitivity in skeletal muscle would lead to the identification of novel therapeutic target for type 2 diabetes." (PMID 25887856, 2015). "Considering type 2 diabetics treated with insulin are more likely to suffer from heart complications, we sought to determine the specific effect of insulin on ceramide-dependent cardiometabolic risk factors, including insulin resistance and altered heart mitochondrial physiology." (PMID 26682540, 2015). "However, failure of beta cell adaptation leads to type 2 diabetes onset with declining insulin secretion and beta cell mass." (PMID 25658116, 2015). "Type 2 diabetes (T2D) mellitus, the most common metabolic disorder in humans, is characterized by hyperglycemia resulting from pancreatic β-cell failure and inadequate insulin secretion to compensate for insulin resistance." (PMID 26379190, 2015). "Another randomized trial examined the replacement of insulin with exenatide in patients with type 2 diabetes and found that glycemic control deteriorated in 38% (11 of 29) of the patients who received exenatide compared with 19% (3 of 16) of the patients who continued insulin." (PMID 25785276, 2015). "Type 2 diabetes (T2D) is characterized by impaired insulin secretion and / or insulin sensitivity." (PMID 26263160, 2015). "Fasting glucose and insulin are intermediate traits for type 2 diabetes." (PMID 25631608, 2015). "In patients with type 1 diabetes the insulin infusion rate begins at roughly 0.5–1 U/hour (mix 100 U short-acting insulin in 100 mL normal saline; i.e., 1 U = 1 mL), whereas infusion rates are typically increased in type 2 diabetics to approximately 2-3 U/hour or higher." (PMID 26078998, 2015). "Indeed, it was shown that DPP-4 inhibitors were effective in Japanese type 2 diabetes patients with higher insulin secreting capacities." (PMID 25699116, 2015). "Type 2 diabetes is recognized as an immune-mediated disease in which cytokines play an important role that leads to impaired insulin signaling and to the selective destruction of the insulin-producing beta cells." (PMID 26199013, 2015). "The metabolic consequence of increased insulin sensitivity in the MLC/mIGF1 animals could include resistance to the establishment of type II diabetes." (PMID 25722973, 2015). "In contrast, overexpression of GLUT4 in skeletal muscle showed lowered blood glucose and increased insulin- or contraction-stimulated glucose transport that could be of benefit in the treatment of type 2 diabetes." (PMID 25713812, 2015). "Moreover, in maturity-onset diabetes of the young (MODY) patients with low insulin responses, there are delayed and decreased insulin and C-peptide secretory responses to glucose due to beta cell dysfunction." (PMID 25894234, 2015). "Thiazolidinediones (TZDs) including troglitazone, pioglitazone, and rosiglitazone are synthetic PPAR γ ligands with the efficacy to enhance insulin sensitivity in animals and humans, and some of the TZDs are already in clinical use as insulin sensitizers in type 2 diabetic patients." (PMID 26146566, 2015). "The absence of pre-existing insulin therapy suggests two possible diagnoses: a) type 2 diabetes-associated DKA or b) a first presentation of type 1 diabetes-associated DKA." (PMID 26715333, 2015). "We hypothesized that sodium salicylate would reduce IKKβ, leading to reduced TNFα and improved insulin signaling in the BBZDR/Wor obese rat model of type 2 diabetes." (PMID 25874611, 2015). "PPAR-γ has emerged as a potent insulin sensitizer and is used in the treatment of type 2 diabetes." (PMID 26083118, 2015).
type 2 diabetes (continued). "Patients with T2DM, which was previously referred to as non-insulin dependent diabetes (NIDDM) or adult onset diabetes, have elevated blood glucose levels secondary to insulin insensitivity and relative insulin deficiency." (PMID 24911161, 2014). "The fact that hyperinsulinemia is a pathological hallmark of type 2 diabetes, along with the structural and functional homology between INSR and IGF1R, prompted us to further investigate the potential roles of insulin and INSR in PCa development and progression." (PMID 24434591, 2014). "Also, many of the insulin target tissues in Drosophila are functionally equivalent with adipose, liver, brain, kidney and skeletal muscle, all known to be important in type 2 diabetes." (PMID 25329475, 2014). "Leptin resistance impairs peripheral glucose homeostasis by decreasing the hypothalamic response to insulin that may lead to the onset of type 2 diabetes." (PMID 25587271, 2014). "Insulin sensitivity is improved following leptin administration, and leptin has been found to decrease glucagon levels in rat and mouse models of both type 1 and type 2 diabetes, contributing to the improvement in glycemic status." (PMID 24987413, 2014). "Therefore, prevention and control of decreases in insulin-secreting ability are important to prevent type 2 diabetes in Japanese individuals." (PMID 25166121, 2014). "In 2003 two noteworthy publications demonstrated the involvement of adipose tissue macrophage infiltration in obesity and insulin sensitivity, since then the importance of these findings for the development of insulin resistance and type 2 diabetes has been under investigation." (PMID 25148116, 2014). "Besides the well-established approaches to improve insulin action and secretion in patients with type 2 diabetes, there is still a demand for alternative therapies." (PMID 24643026, 2014). "Type 2 diabetics also display an insulin resistance of protein metabolism at the whole body level." (PMID 25302072, 2014). "FFAR2 agonists could be used as novel insulin-sensitizing drugs for the treatment of type 2 diabetes." (PMID 25414667, 2014). "In addition, an accumulation of secondary messenger lipid species such as DAG or ceramide, also contributes to muscle insulin resistance, thereby exacerbating the severity of type 2 diabetes." (PMID 24962347, 2014). "Most type 2 diabetes patients eventually require insulin treatment if survival is long enough." (PMID 24667573, 2014). "Thus, understanding factors that regulate insulin transcription and translation is critical to prevent or delay the development of type 2 diabetes." (PMID 25628604, 2014). "Consequently, the increase in the number of overweight Japanese individuals who have low insulin-secreting ability is likely to be reflected by further increases in the number of Japanese individuals with type 2 diabetes." (PMID 25166121, 2014). "stimulate the pancreas to make more insulin and are used in the treatment of type 2 diabetes." (PMID 25481012, 2014). "This alteration in the abundance of two forms might be related to the insulin resistance and the decreased sensitivity for metabolic actions of insulin in type 2 diabetes." (PMID 25988147, 2014). "This led us to suspect that this group consists mostly of type 2 diabetics who are insulin-dependent (relative insulin deficiency) rather than type 1 diabetics (absolute insulin deficiency)." (PMID 24919660, 2014). "Recent data indicate INS and DI as the best predictors of future type 2 diabetes in adults." (PMID 24498035, 2014). "FCP and PGCP have also been found to predict the need for insulin treatment in type 2 diabetes." (PMID 25945127, 2014). "In the network analysis with type 2 diabetic patients, the hierarchical cluster revealed that insulin-related variables such as plasma insulin, C-peptide and HOMA-IR were categorized into a group that was different from that of glucose-related variables such as FPG, HbA1c, GA and 1,5-AG." (PMID 25177913, 2014).
type 2 diabetes (continued). "Framework analysis provided a structured, rigorous approach to analysing the resulting data with a focus on the roles and relationships between health professionals involved in the initiation of insulin for people with type 2 diabetes in the general practice setting." (PMID 24479762, 2014). "Moreover, endogenous and chemical chaperones are able to ameliorate induced ER stress and increase insulin secretion, suggesting that improving chaperone capacity can play an important role in improving beta-cell function in type 2 diabetes." (PMID 25010593, 2014). "The GK rat is a model of nonobese type 2 diabetes with defective insulin secretion associated with impaired glucose metabolism in pancreatic β cells." (PMID 25373904, 2014). "More mysterious is the transient elevation of β-cell proliferation in Perk heterozygotes, which is unlikely to be due to a normal compensatory response in response to hyperglycemia and an increase demand for insulin similar to that seen in the progression to type 2 diabetes." (PMID 24915520, 2014). "Impaired insulin secretion contributes to hyperglycemia in type 2 diabetes." (PMID 25412338, 2014). "The aim of the present study is to evaluate the effect of add-on of sitagliptin on blood glucose control or glucose fluctuation as well as the tolerability of this combination therapy in more than 200 Japanese type 2 diabetic patients treated with insulin and/or other OHA in real clinical practice." (PMID 27419209, 2014). "Sulfonylurea agents or metformin may be used in conjunction with insulin and pramlintide in the treatment of type 2 diabetes." (PMID 26237392, 2014). "If this compensatory rise in insulin production is not maintained by the pancreas, causing insulin levels to drop, then type 2 diabetes ensues." (PMID 25486190, 2014). "Several clinical studies have supported that addition of glimepiride in the subjects with poorly controlled insulin-treated type 2 diabetes could improve glycemic control and reduce insulin requirements." (PMID 24650537, 2014). "The mechanism of action of vitamin D in type 2 diabetes is thought to be mediated not only through regulation of plasma calcium levels, which regulate insulin synthesis and secretion, but it also improves insulin sensitivity of the target cells (liver, skeletal muscle, and adipose tissue)." (PMID 25308347, 2014). "Insulin signalling and glucose transport are critical in maintaining glucose homeostasis and defects in these pathways significantly contribute to the pathogenesis of type 2 diabetes." (PMID 24657708, 2014). "Hypoglycemia is the leading limiting factor in the glycemic management of type 1 and insulin-treated type 2 diabetes and may be an obstacle to the use of insulin." (PMID 24397956, 2014). "Some previous studies have reported that CrPic supplementation could increase insulin sensitivity in subjects with type 2 diabetes." (PMID 25054160, 2014). "The functions of neuroendocrine loop in gut-insulin axis may be very helpful for understanding the role of this axis in pathogenesis of type 2 diabetes." (PMID 25247193, 2014). "In addition, type 2 diabetes is a progressive disease characterized by worsening of glycemia even after starting insulin (analog) treatment." (PMID 24904529, 2014). "Certainly we know that type 2 diabetes patients on insulin are often mislabeled as having type 1 diabetes; this could reduce the odds ratio in that study but only if it were differential between cases and controls." (PMID 24155126, 2014). "Therefore, there comes to an international clinical consensus to recommend patients use metformin in combination with insulin in type 2 diabetes patients who initiate insulin treatment." (PMID 25202328, 2014). "However, non-insulin-dependent (basal) glucose uptake is also impaired in patients with type 2 diabetes." (PMID 24849570, 2014).
type 2 diabetes (continued). "Whole wheat bread and white wheat bread give the same postprandial response of glucose and insulin in type 2 diabetic patients; however, the inclusion of a high percentage of intact or partially milled cereal kernels in the flour reduces the glycemic response of bread." (PMID 25325250, 2014). "Of great clinical interest, synthetic ligands of PPARγ, belonging to the class of thiazolidinediones (TZDs), such as troglitazone, pioglitazone, and rosiglitazone, function as insulin sensitizers and are used for treating hyperglycemia in patients with type 2 diabetes." (PMID 24790595, 2014). "Among several pathways involved in the pathogenesis of the epidemically spreading disease type 2 diabetes, an altered secretory pattern of the expanded and inflamed adipose tissue is thought to be important for the regulation of insulin sensitivity and subclinical inflammation in various tissues." (PMID 24643166, 2014). "When applied to subjects with metabolic syndrome (MS) or type 2 diabetes (t2DM) the therapy improves the diverse parameters inherit to metabolic syndrome (MS) and type 2 diabetes (t2DM)—inflammation, hypertension, glycemia, dyslipidemia, abdominal obesity, body weight, and insulin signaling." (PMID 26137508, 2014). "Type 2 diabetes is characterised by an age-related decline in insulin secretion." (PMID 25532126, 2014). "A phase IIB study in patients with Type 2 diabetes given an antagonist to the enzyme 11β-HSD-1 responsible for conversion of corticosteroids to cortisol showed increased insulin sensitivity and improvement in: glycemic control, total cholesterol, LDL-cholesterol and triglycerides." (PMID 25183952, 2014). "Another study based on the French National Healthcare Insurance system database also showed no excess risk of cancer in patients with type 2 diabetes on insulin glargine compared with those on human insulin." (PMID 25329887, 2014). "In addition to insulin insensitivity, type 2 diabetic patients display lowered GLP-1 concentrations and a reduced ability to promote insulin secretion." (PMID 24712679, 2014). "While type 1 diabetes management requires insulin and thus leaves little choice during pregnancy, type 2 diabetes may be managed with life-style modifications, oral anti-diabetic agents, and/or insulin." (PMID 24438493, 2014). "Insulin therapy remains underutilized in geriatric populations despite the fact that many geriatric patients with a history of type 2 diabetes could benefit from the use of insulin to achieve improved glycemic control." (PMID 23959960, 2014). "In type 2 diabetes, GB improves insulin sensitivity, as defined by hyperinsulinemic euglycemic clamps, in parallel with reduced basal insulin levels and increased postprandial insulin secretion." (PMID 24668543, 2014). "Ninteen patients were under oral medication or insulin therapy for type II diabetes mellitus." (PMID 25375257, 2014). "Target prediction and GO analysis suggested that these differentially expressed miRNAs potentially targeted many genes which were related to apoptosis, regulation of metabolic process, intracellular signaling cascade, insulin signaling pathway and type 2 diabetes." (PMID 24983625, 2014). "However, individuals with Type 2 diabetes and high liver fat had higher fasting glucose and insulin levels, lower GIRs, and a corresponding higher M/I index and sustained higher insulin levels throughout the protocol than those with low liver fat." (PMID 25104497, 2014). "Thyroid disease may be a marker of a distinct metabolic trait in type 2 diabetes potentially requiring earlier insulin treatment." (PMID 24580798, 2014). "Tissue-specific markers of IR, Matsuda IR and Adipocyte IR, were superior to fasting plasma insulin level in predicting worsening of hyperglycemia, and Liver IR was superior to fasting insulin level in predicting incident type 2 diabetes and cardiovascular events." (PMID 25310839, 2014).
type 2 diabetes (continued). "Once such points have been clarified, our structured treatment regimen might be beneficial for many type 2 diabetes patients requiring insulin therapy." (PMID 24684803, 2014). "Therefore, an alternative therapeutic approach has been to develop longer lasting peptides to prolong insulin secretion, reducing blood glucose levels in patients with Type 2 diabetes." (PMID 24712679, 2014). "While PPAR-gamma agonists have great therapeutic potential in the treatment of type 2 diabetes for their potent insulin-sensitizing activity and anti-diabetic effects, it is unclear whether phthalates modulate PPAR-gamma in the same way." (PMID 24499162, 2014). "Additionally, another randomized, vehicle-controlled clinical trial with 81 participants showed that vitamin D3 supplementation (4000 IU) for 6 months significantly improved insulin sensitivity and fasting insulin level in type 2 diabetic women." (PMID 25160946, 2014). "Confirming these results, other studies have shown that subclinical systemic inflammation in obese patients, as measured by elevated levels of CRP, IL-6, and TNF-α, predicts the development of type 2 diabetes and contributes to a decrease of insulin sensitivity in peripheral tissues." (PMID 25548896, 2014). "Fasting insulin (FI), fasting glucose (FG), systolic blood pressure (SBP), high density lipoproteins (HDL), triacylglycerides (TAG), and body mass index (BMI) are well-known risk factors for type 2 diabetes." (PMID 25960772, 2014). "In cultured primary human skeletal muscle, manipulating PTP1B expression levels inversely modulates insulin-induced Akt phosphorylation, and increased PTP1B expression in skeletal muscle of patients with type 2 diabetes is associated with decreased whole-body insulin sensitivity." (PMID 25398386, 2014). "In recent years, β2 arrestins have been shown to be involved with regulation of insulin action and inflammatory signal pathway, particularly in type 2 diabetes, and thus could be of interest as regulators of insulin sensitivity in CF." (PMID 25299696, 2014). "In the present study, we found that SNPs associated with DNA methylation, mRNA expression and insulin secretion in human pancreatic islets also showed nominal associations with type 2 diabetes as reported by the DIAGRAM consortium and with glucose/insulin traits as reported by MAGIC investigators." (PMID 25375650, 2014). "Strategies to slow or even prevent islet mtDNA depletion in man could help to preserve insulin secretion and delay the development of type 2 diabetes." (PMID 25532126, 2014). "A study of 64 overweight adults with a family history of type 2 diabetes showed that pancreatic fat was associated with whole body insulin sensitivity and with glucose tolerance status, but not with beta-cell function per se." (PMID 24669786, 2014). "These detailed metabolic studies show that blocking cortisol action in patients with Type 2 diabetes has significant metabolic effects, leading to insulin sensitization in both adipose tissue and the liver, with associated reductions in fasting plasma glucose concentrations and hyperinsulinemia." (PMID 25104497, 2014). "Type 2 diabetes is a progressive disease with multiple factors contributing to hyperglycemia—insulin resistance in muscle, liver, and adipose tissue, increased hepatic glucose production, and decreased insulin secretion." (PMID 24565221, 2014). "Moreover, angiotensin II seems to play a role in the regulation of insulin secretion by pancreatic beta-cells and insulin sensitivity by peripheral tissues, which are two critical factors contributing to the development of type 2 diabetes." (PMID 24734227, 2014). "Relative to the effect of continuous aerobic exercise, HIIT has also been shown to induce comparable improvements in fitness and insulin sensitivity in clinical populations, including those with overweight/obesity, cardiovascular disease, metabolic syndrome, and type 2 diabetes." (PMID 24669314, 2014).